TMEM256 (transmembrane protein 256)
Synonyms: C17orf61; MGC40107
Tractability: Antibody: UniProt predicts a signal peptide or a membrane-spanning region. PROTAC: ubiquitination databases record sites on it.
Gene: Protein-coding gene on chromosome 17 (7,402,975 to 7,404,097, reverse strand). Ensembl gene ENSG00000205544.
Subcellular location: Membrane
Subcellular location (Human Protein Atlas): Vesicles
Gene Ontology:
Cellular component: extracellular exosome; mitochondrion; membrane
Genetic constraint (gnomAD): Loss-of-function variants: 14 observed, 14.25 expected, observed/expected ratio (o/e) 0.98, 90% interval 0.65 to 1.53. The upper end of that interval is the gene's LOEUF score, 1.53, which puts it in group 6 of 6, group 1 being the genes least tolerant of losing a copy. Missense variants: 146 observed, 137.44 expected, observed/expected ratio (o/e) 1.06, 90% interval 0.93 to 1.22. Synonymous variants: 68 observed, 61.25 expected, observed/expected ratio (o/e) 1.11, 90% interval 0.91 to 1.36.
Homologues: Orthologues: chimpanzee TMEM256 (99% identical), macaque TMEM256 (97% identical), mouse Tmem256 (89% identical), guinea pig TMEM256 (85% identical), dog TMEM256 (76% identical), rat Tmem256 (73% identical), zebrafish tmem256 (50% identical), Caenorhabditis elegans Y106G6H.8 (38% identical), Drosophila melanogaster CG42395 (36% identical), Drosophila melanogaster CG4686 (35% identical). Paralogues in human: RBKS (22% identical), KHK (16% identical), ADK (9% identical).
Diseases named in the same sentence as TMEM256 in open-access papers:
TMEM256 is named in the same sentence as 3 diseases in open-access papers, as found by Europe PMC text mining. Sharing a sentence is not in itself a finding about the gene and the disease. The quoted sentences say what the papers report.
prostate carcinoma (2 papers, 2015 to 2022). A carcinoma that arises from epithelial cells of the prostate gland. "One of the comprehensive proteomic studies of prostate cancer described in a review suggested that TMEM256 displayed excellent accuracy for cancer diagnosis with a high AUC of 0.94 in clinical urinary samples." (PMID 35757760, 2022). "Nevertheless, in the discussion of another review, though another group proposed TMEM256 as a potential biomarker for prostate cancer, two other groups could not detect the presence of TMEM256 in two sets of clinical urinary samples." (PMID 35757760, 2022).
TMEM256 also shares sentences with these, for which no sentence is quoted: ciliopathy (1 paper); peanut allergy (1).